BRAF (B-Raf proto-oncogene, serine/threonine kinase)
Diseases named in the same sentence as BRAF in open-access papers (continued):
Sharing a sentence is not in itself a finding about the gene and the disease.
colorectal cancer (continued). "In retrospect, this unique characteristic of COLO 320DM cells compared to the other CIMP− cell lines might have enabled these cells to tolerate mutant BRAF overexpression, and may explain our difficulties in obtaining BRAFV600E expressing clones in other colorectal cancer cell line such as Caco-2." (PMID 20027224, 2009). "However, its association with BRAF mutation and CIMP+ status in human colorectal cancers has not been explored." (PMID 20027224, 2009). "HT29 colorectal cancer cells expressing the BRAF V600E mutation showed an increased activation of YAP and cytosolic CLDN4 whilst a decrease in membranous CLDN4, compared to HCT116 BRAF wild-type cells, which showed no YAP activation or changes in CLDN4 when treated with CPE for 24 h." (PMID 39340753, 2024). "However, this therapy is not suitable for BRAF-mutant colorectal cancer." (PMID 39529955, 2024). "Combinations of BRAF inhibitors with PI3K inhibitors have not been studied in a systematic manner in colorectal cancer, but few available retrospective data suggest that parallel inhibition of the two mutated oncogenes may provide a synergistic effect in double mutant cancers." (PMID 36295658, 2022). "However, as anti-EGFR antibody treatment induces ADCP of human colorectal cancer cells by macrophages, independent of mutations in EGFR signaling pathways, mutations in KRAS or BRAF are not expected to negatively impact the efficacy of preoperative antibody treatment to eliminate CTCs." (PMID 35035479, 2022). "However, BRAF V600E has no predictive value for BRAF inhibitors in colorectal cancer patients." (PMID 29368597, 2018). "In addition, to further elucidate whether the altered expression of the candidate miRNAs occurred in a BRAF-dependent fashion, we added KRAS-mutant colorectal cancers (n = 20) to the qRT-PCR and compared the miRNA expressions between BRAF-mutant tumors and KRAS-mutant tumors." (PMID 29115941, 2017). "Moreover, BRAF inhibitors are not used as a standard treatment for colorectal cancer." (PMID 29262612, 2017). "Is the lack of response in colorectal cancer due to the presence of additional anomalies that co-occur with BRAF mutations, or because BRAF inhibition causes feedback activation of EGFR, or because BRAF mutations are not driver abnormalities in colorectal cancer?" (PMID 25593991, 2014). "Furthermore, mutations in the PTEN gene, although likely to be rare in unselected colorectal cancers, are associated with MSI+ and BRAF mutations, whereas loss of PTEN expression is not and may be due mostly to other mechanisms." (PMID 21473780, 2011). "We assessed the response to DUSP4 depletion in two BRAF-mutant nonmelanoma cell lines (the glioma line DBTRG and the colorectal carcinoma cell line, LS411N) that were sensitive to MAPK inhibitors." (PMID 35580987, 2022). "Unlike the routine detection of HER2, EGFR, BRAF, KRAS and other genes in breast cancer, lung cancer, colorectal cancer and other tumors, HCC has not yet an apparent gene-phenotype related to its prognosis and treatment due to its heterogeneity." (PMID 35071004, 2021). "In selected colorectal cancer cell lines, AZ304 significantly inhibited cell growth in vitro and in vivo, regardless of BRAF genetic status." (PMID 29755114, 2018). "PTEN status was not prognostic for survival in advanced colorectal cancer, irrespective of KRAS or BRAF status." (PMID 23930204, 2013). "Even though tumors of all clinico-pathological subtypes were represented among the biomarker panel methylation positive samples, the very few negative colorectal cancers were generally of the MSS phenotype and were BRAF wild-type, compatible with CIMP negative tumors." (PMID 21777459, 2011).
metastatic melanoma (1,142 papers, 2004 to 2026). A melanoma that has spread from its primary site to another anatomic site. "The overall response rate of BRAF mutation-positive, unresectable or metastatic melanoma patients is higher with the treatment of binimetinib plus encorafenib (63%) compared to vemurafenib (40%)." (PMID 41584037, 2026). "The confirmed tumor response rate of BRAF mutation-positive, unresectable or metastatic melanoma patients is higher with the treatment of trametinib (22%) compared to chemotherapy (8%)." (PMID 41584037, 2026). "The BRAF mutation in the patient with a metastatic melanoma harbored a different but closely related BRAF mutation, namely p.A598_T599insV (insertion of valine), whereas our patient exhibited a p.A598_T599insI mutation (insertion of isoleucine)." (PMID 40765221, 2025). "BRAF/MEK inhibitors (BRAFi/MEKi) improve outcome in patients with BRAF-mutated metastatic melanoma but are associated with cardiotoxicity, leading to a decline in left ventricular ejection fraction (LVEF)." (PMID 40223207, 2025). "Activating mutations in BRAF are the most common alterations and are found in approximately 50% of metastatic melanoma." (PMID 40362630, 2025). "BRAF inhibitors such as VEM are currently approved as first-line treatments for patients with mutated BRAF metastatic melanoma." (PMID 40076912, 2025). "This study demonstrated the efficacy of vemurafenib (PLX4032), a selective BRAF kinase inhibitor, in treating metastatic melanoma with the BRAF V600E mutation." (PMID 39897423, 2025). "Vemurafenib is an oral BRAF inhibitor approved for the treatment of patients with inoperable or metastatic melanoma harboring the BRAF V600E mutation." (PMID 40872552, 2025). "Among patients with metastatic melanoma, the discovery of activating mutations in the BRAF gene—particularly the BRAF V600E mutation, which occurs in approximately 40%–60% of cases—has revolutionized therapeutic strategies." (PMID 39897423, 2025). "Targeted therapy with BRAFi has significantly improved outcomes for patients with BRAF-mutated metastatic melanoma." (PMID 40943167, 2025). "This prospective, observational study analyzed fecal and blood samples from 26 patients diagnosed with BRAF-mutated metastatic melanoma." (PMID 40659866, 2025). "Author-targeted therapy with vemurafenib allowed significant advances in the treatment of BRAF-mutated metastatic melanoma." (PMID 40141318, 2025). "A 60-year-old male with a history of stage IIIb BRAF-mutated metastatic melanoma, diagnosed 14 months prior, presented with a several-week history of thirst, polyuria, and polydipsia." (PMID 40575214, 2025). "Studies have demonstrated that the presence of a BRAF mutation and the use of BRAF inhibitors are both associated with significantly worse treatment responses to ICIs in patients with metastatic melanoma." (PMID 41010951, 2025). "The approval of the BRAF inhibitor vemurafenib marked a significant advancement in the treatment of metastatic melanoma harboring BRAF V600 mutations." (PMID 40861441, 2025). "Patients with metastatic melanoma should have metastases (preferably) or the primary tumour screened for the detection of BRAF V600 mutation [IV, A; ESCAT score: I-A]." (PMID 39550033, 2025). "This approach, which combined dabrafenib–trametinib or vemurafenib–cobimetinib, received FDA approvals in 2014 and 2015, respectively, for treating unresectable or metastatic melanoma with BRAF mutations." (PMID 40332392, 2025). "BRAF inhibitors like Vemurafenib and Dabrafenib are used alone or in combination with MEK inhibitors to treat patients with BRAF-mutated metastatic melanoma." (PMID 41155168, 2025). "BRAF mutations are recognized in approximately 45% of patients with metastatic melanoma and BRAF and MEK inhibitors induce rapid response and prolong survival." (PMID 41160271, 2025). "A previous study of patients with metastatic melanoma quantified the level of the BRAF V600E-mutated protein." (PMID 40075679, 2025).
metastatic melanoma (continued). "Trametinib, which is a MEK inhibitor, was found to be effective against BRAF V600E-mutated metastatic melanoma." (PMID 40943615, 2025). "This studyprovides pivotal evidence for the clinical efficacy of trametinib, a selective MEK1/2 inhibitor, in treating metastatic melanoma with BRAF V600E or V600K mutations." (PMID 39897423, 2025). "In human medicine, the detection of BRAF mutations in metastatic melanoma patients opened the possibility of BRAF/MAPK-targeted therapy with selective BRAF inhibitors (BRAFi), for instance, vemurafenib or dabrafenib." (PMID 39591358, 2024). "For instance, the upregulation of PD-L1 has been associated with increase resistance to cisplatin in patients with small cell lung cancer, and resistance to BRAF inhibitors in patients with metastatic melanoma is similarly linked to PD-L1." (PMID 38312647, 2024). "Despite not having been approved for monotherapeutic use, the second-generation BRAF inhibitor encorafenib is FDA-approved for the treatment of unresectable or metastatic melanomas with BRAF V600E and V600K mutations." (PMID 38539548, 2024). "Combination therapies can also involve three drugs, such as in the case of vemurafenib, cobimetinib, and the PD-L1 blocking antibody atezolizumab; this trio was FDA-approved for treating unresectable or metastatic melanomas with any BRAF V600 mutation." (PMID 38539548, 2024). "The effect of BRAF mutation on metastatic melanoma is controversial, though our study found that metastatic patients with BRAF mutations in the TCGA-SKCM cohort had favorable survival (P = 0.024)." (PMID 38229080, 2024). "BRAF inhibitors had already set a high standard in treating BRAF-mutated metastatic melanoma by directly targeting and inhibiting the mutated BRAF protein." (PMID 39328691, 2024). "In 2015, the FDA approved the combination of vemurafenib and the MEK inhibitor cobimetinib for the treatment of unresectable or metastatic melanoma with BRAF V600E or V600K mutations." (PMID 39529955, 2024). "The BRAF V600E mutation, situated within the protein tyrosine kinase domain, was detected in 7 out of 26 samples within the metastatic melanoma cohort." (PMID 39669561, 2024). "Our study aimed to evaluate the efficacy, that is, progression‐free survival (PFS), overall survival (OS) and objective response rate (ORR) of anti‐PD‐1 monotherapy and BRAF/MEK inhibition therapy in patients with BRAF‐mutated metastatic melanoma." (PMID 38491825, 2024). "Vemurafenib (Zelboraf; Plexxikon/Roche) is the first drug approved for the treatment of BRAF mutation metastatic melanoma in the United States in August 2011 and in the European Union in February 2012." (PMID 38775844, 2024). "Malignancies that are caused by v-Rapidly accelerated fibrosarcoma viral oncogene homolog B1 (BRAF) mutations, such as metastatic melanoma, can potentially be treated with BRAF inhibitors, such as vemurafenib and dabrafenib." (PMID 39186376, 2024). "In 2015, the European Union approved the combination of dabrafenib and the MEK inhibitor trametinib ("D + T" regimen) for the treatment of adult patients with unresectable or metastatic melanoma positive for the BRAF V600 E/K mutation." (PMID 39529955, 2024). "In 2011, the FDA approved vemurafenib for the treatment of adult patients with BRAF V600E mutation in unresectable or metastatic melanoma." (PMID 39529955, 2024). "Upregulation of EGFR has also been associated with BRAF inhibitor resistance, indicating a potential role for ctDNA in early identification of resistance to vemurafenib and dabrafenib in metastatic melanoma." (PMID 39156972, 2024). "The BRAF inhibitor vemurafenib is the standard treatment for unresectable or metastatic melanomas harboring activating BRAF V600E mutations." (PMID 38540310, 2024). "Although the majority of these patients experience clinical benefit from BRAF and MEK inhibitors, most patients with BRAF V600-mutated metastatic melanoma develop resistance to these agents." (PMID 39000050, 2024).
metastatic melanoma (continued). "We performed a retrospective analysis of patients with BRAF‐mutated metastatic melanoma treated with BRAF/MEK inhibition therapy or anti‐PD‐1 monotherapy (nivolumab or pembrolizumab)." (PMID 38491825, 2024). "Therapies targeting mutations other than BRAF have been shown to be efficacious for metastatic melanoma in the second-line setting." (PMID 39542696, 2024). "For patients diagnosed with BRAF-mutated metastatic melanoma exhibiting extensive and symptomatic disease, the preferred initial treatment approach is to initiate targeted therapy utilizing BRAF and MEK inhibitors." (PMID 38891988, 2024). "SECOMBIT was a clinical trial testing different sequences of immunotherapy (ipilimumab plus nivolumab) and targeted therapy (encorafenib plus binimetinib) for untreated BRAF-mutated metastatic melanoma." (PMID 38167503, 2024). "Although vemurafenib is a BRAF mutant inhibitor with high selectivity and efficacy against metastatic melanoma with BRAF V600 and non-V600E mutations, treatment resistance develops in most patients." (PMID 38183141, 2024). "In clinical practice, the detection of BRAF mutations is a critical factor in treatment decisions, particularly for metastatic melanoma." (PMID 38474231, 2024). "In patients with a BRAF V600 mutation, eight/nine were found at the time of initial diagnosis of metastatic melanoma." (PMID 38339344, 2024). "All these combination regimens showed long-term benefits as first-line treatment in patients who had unresectable or metastatic melanoma with a BRAF V600E or V600K mutation." (PMID 38201012, 2024). "The FDA endorsed the use of a combination of dabrafenib (a BRAF inhibitor) and trametinib (a MEK inhibitor) for treating metastatic melanoma with BRAF mutations." (PMID 39569013, 2024). "Trametinib is clinically approved for the treatment of NRAS/BRAF-mutated metastatic melanoma; however, data showing efficacy in combination with immunotherapies are still lacking." (PMID 39286984, 2024). "Recommended therapy for patients with metastatic melanoma with a BRAF V600-mutation includes combination regimens targeting BRAF and MEK (eg, dabrafenib plus trametinib, vemurafenib plus cobimetinib, or encorafenib plus binimetinib)." (PMID 38725995, 2024). "This is perfectly illustrated by the BRAF V600E mutation that can be effectively targeted by single agent or combined BRAF plus MEK inhibition in metastatic melanoma." (PMID 37982847, 2024). "The main drawback of BRAF/MEK inhibitors (BRAF/MEKi)-based targeted therapy in the management of BRAF-mutated cutaneous metastatic melanoma (MM) is the development of therapeutic resistance." (PMID 38755661, 2024). "The median PFS with single-agent BRAF inhibitors in BRAF-mutated metastatic melanoma is around 5–6 months." (PMID 38203795, 2024). "The expression of selected 90 lncRNAs in serum from 30 metastatic melanoma patients with confirmed mutations in the BRAF V600 E or K gene was studied." (PMID 38601651, 2024). "Currently, the approved indication for vemurafenib monotherapy in China is for unresectable or metastatic melanoma positive for the BRAF V600 mutation as determined by a China FDA-approved testing method." (PMID 39529955, 2024). "For example, trametinib, a representative MEK inhibitor, is used as a monotherapy for unresectable or metastatic melanoma with BRAF-V600E or V600K mutations." (PMID 38504158, 2024). "The median PFS with the combination therapy was comparable to the reports with combination BRAF and MEK inhibitors in patients with BRAF-mutated metastatic melanoma." (PMID 39594689, 2024). "Selective BRAF and MEK inhibitors are the current standard treatments for metastatic melanoma, and the determination of BRAF mutations is a necessary step before treatment selection." (PMID 39200941, 2024).
metastatic melanoma (continued). "The BRIM-3 clinical trial substantiated that vemurafenib markedly enhanced OS and progression-free survival (PFS) in patients with untreated, metastatic melanoma harboring the BRAF V600E mutation, as compared to the use of dacarbazine." (PMID 39610923, 2024). "In June 2018, they both received their first approval in the United States for their combined use in patients with unresectable or metastatic melanoma with a BRAF V600E or -V600K mutation." (PMID 39392364, 2024). "The approval was based on the phase III randomized active-controlled three-arm COLUMBUS trial, which evaluated the combined encorafenib–binimetinib vs. encorafenib alone or vemurafenib alone in patients with BRAF-mutated unresectable or metastatic melanoma." (PMID 38203795, 2024). "In 2013, the FDA approved dabrafenib as a single-agent treatment for adult patients with unresectable or metastatic melanoma carrying the BRAF V600E mutation." (PMID 39529955, 2024). "A study published in N Engl J Med in 2010 showed that BRAF inhibitors effectively treat most patients with metastatic melanoma carrying the BRAF V600E mutation, leading to complete response or partial response." (PMID 39610923, 2024). "To date, the molecular characterization of metastatic melanomas for predictive purposes has primarily relied on the assessment of BRAF mutations for the use of BRAF inhibitors." (PMID 38667446, 2024). "Vemurafenib and dabrafenib are BRAF inhibitors approved by the US Food and Drug Administration for treating metastatic melanoma, especially for patients harboring distant metastases with BRAF mutations." (PMID 38254853, 2024). "Based on these findings, vemurafenib and dabrafenib were approved by the FDA for the treatment of unresectable or metastatic melanomas carrying the BRAF V600E mutation." (PMID 39246323, 2024). "In 2018, the FDA approved the combination of encorafenib and binimetinib for first-line treatment of patients with unresectable or metastatic melanoma with BRAF V600 E/K mutations." (PMID 39529955, 2024). "when multiple patients with BRAF V600E-mutated metastatic melanoma had complete or partial tumor regression with a BRAF inhibitor." (PMID 39542696, 2024). "The BRAF V600 mutation is found in approximately 35–50% of metastatic melanomas and is associated with increased disease aggressiveness and reduced survival." (PMID 37569757, 2023). "BRAF V600 mutation-positive unresectable or metastatic melanoma in adults is treated with the selective competitive inhibitor of BRAF kinase dabrafenib as monotherapy or in combination with the MEK inhibitor trametinib." (PMID 36614330, 2023). "BRAF V600E mutation was found in six cases of metastatic melanomas of the head and neck, of which three cases were positive for this mutation, as compared with the 23 cases of acral melanomas, which tested negative for the same mutation." (PMID 37649946, 2023). "It has been proven efficacious in the management of metastatic melanoma, a malignancy frequently mutated for BRAF." (PMID 37397394, 2023). "Metastatic melanoma is a refractory genetic disease, particularly 50% of tumors associated with the wild-type BRAF." (PMID 37833287, 2023). "Studies have demonstrated that regulation of the MAPK signaling pathway by targeting BRAF kinase is already the standard of care for patients with metastatic melanoma containing BRAF mutations." (PMID 36770611, 2023). "The first approved BRAF kinase inhibitor vemurafenib, as the first-line drug for BRAF-mutated metastatic melanoma, exhibited significantly clinical effects." (PMID 36834830, 2023). "The driver mutation of BRAF is found in approximately 50% of metastatic melanomas and represents a target for focused therapies in a population of patients with the aggressive disease." (PMID 36995534, 2023). "Multiple selective BRAF inhibitors (BRAFis) have been used in combination with MEK inhibitors for the treatment of BRAF-mutated metastatic melanoma." (PMID 38116009, 2023).